PEX1 (peroxisomal biogenesis factor 1)
Description:
Component of the PEX1-PEX6 AAA ATPase complex, a protein dislocase complex that mediates the ATP-dependent extraction of the PEX5 receptor from peroxisomal membranes, an essential step for PEX5 recycling. Specifically recognizes PEX5 monoubiquitinated at 'Cys-11', and pulls it out of the peroxisome lumen through the PEX2-PEX10-PEX12 retrotranslocation channel. Extraction by the PEX1-PEX6 AAA ATPase complex is accompanied by unfolding of the TPR repeats and release of bound cargo from PEX5.
Synonyms: HMLR1; PBD1A; PBD1B; ZWS; ZWS1
Tractability: PROTAC: ubiquitination databases record sites on it; its protein half-life has been measured.
Gene: Protein-coding gene on chromosome 7 (92,487,020 to 92,528,640, reverse strand). Ensembl gene ENSG00000127980.
Subcellular location: Cytoplasm, cytosol; Peroxisome membrane
Subcellular location (Human Protein Atlas): Peroxisomes
Pathways (Reactome):
Protein localization: Peroxisomal protein import
Gene Ontology:
Molecular function: ATP binding; ATP hydrolysis activity; membrane protein dislocase activity; protein binding; protein-containing complex binding; ubiquitin-modified protein reader activity
Biological process: microtubule-based peroxisome localization; peroxisome organization; protein import into peroxisome matrix; protein import into peroxisome matrix, receptor recycling; protein targeting to peroxisome; protein unfolding
Cellular component: ATPase complex; cytoplasm; cytosol; extracellular exosome; peroxisomal membrane; peroxisome
Genetic constraint (gnomAD): Loss-of-function variants: 59 observed, 98.28 expected, observed/expected ratio (o/e) 0.6, 90% interval 0.49 to 0.75. The upper end of that interval is the gene's LOEUF score, 0.75, which puts it in group 3 of 6, group 1 being the genes least tolerant of losing a copy. Missense variants: 961 observed, 1,115.5 expected, observed/expected ratio (o/e) 0.86, 90% interval 0.82 to 0.91. Synonymous variants: 356 observed, 399.27 expected, observed/expected ratio (o/e) 0.89, 90% interval 0.82 to 0.97.
Gene-disease validity (ClinGen):
ClinGen rates the evidence that PEX1 causes each of these diseases.
peroxisome biogenesis disorder due to PEX1 defect (autosomal recessive): Definitive. Any Zellweger spectrum disorder in which the cause of the disease is a mutation in the PEX1 gene.
Homologues: Orthologues: chimpanzee PEX1 (99% identical), macaque PEX1 (98% identical), pig PEX1 (89% identical), dog PEX1 (86% identical), guinea pig PEX1 (85% identical), mouse Pex1 (82% identical), rat Pex1 (81% identical), rabbit PEX1 (81% identical), tropical clawed frog pex1 (51% identical), zebrafish pex1 (47% identical), Drosophila melanogaster Pex1 (23% identical), Caenorhabditis elegans prx-1 (22% identical). Paralogues in human: VCP (18% identical), AFG2A (17% identical), NVL (17% identical), PEX6 (17% identical), AFG2B (17% identical).